HIF1A (hypoxia inducible factor 1 subunit alpha)
Diseases named in the same sentence as HIF1A in open-access papers (continued):
Sharing a sentence is not in itself a finding about the gene and the disease.
pulmonary hypertension (continued). "The inhibition of myeloid‐specific HIF‐1α may be a novel therapeutic strategy for the treatment of pulmonary hypertension." (PMID 30927327, 2019). "We demonstrated that expression of several genes was attenuated by HIF‐1α deletion in macrophages, which may play a critical role in the development of pulmonary hypertension." (PMID 30927327, 2019). "Studies examining the effect of the suppression of AhR in combination with suppression of HIF-1α in pulmonary arterial hypertension could prove to be useful." (PMID 29984241, 2018). "MITF stimulates the transcription of HIF1A, which contributes to pulmonary hypertension." (PMID 28002425, 2016). "Interestingly, increased lung HIF-1α expression is also evident in a lamb model of pulmonary hypertension secondary to congenital heart disease and vascular stress from increased pulmonary blood flow." (PMID 25814954, 2015). "Because heterozygous mice lacking one HIF-1α allele display attenuated hypoxia-induced pulmonary vascular remodeling and pulmonary hypertension, HIFs are believed to play an important role in pulmonary vascular signaling." (PMID 25814954, 2015). "Research into the pathogenesis of HPH has revealed that HIF-1α plays an important role in pulmonary vascular constriction, vascular remodeling and the development of pulmonary hypertension, possibly by regulating the expression levels of ET-1 and ADM at a transcriptional level." (PMID 24944643, 2014). "Selective ET-1-A antagonist can inhibit hypoxic pulmonary vessel contraction, inhibit or decrease pulmonary hypertension under hypoxia, through which hypoxia can regulate ET-1 gene expression via inducing HIF-1α and ET-1 levels were linearly correlated with pulmonary artery pressure." (PMID 22363556, 2012). "In addition, HIF-1α and HIF-2α have been implicated in the pathogenesis of pulmonary hypertension, which may represent an important marker for determination of high-altitude pulmonary edema susceptibility." (PMID 36244759, 2022). "The recent studies have shown that HIF-1α has a crucial role in critical aspects of cell metabolism and mammalian embryogenesis, and contributes to pathogenesis for a variety of diseases, such as hereditary erythrocytosis, pulmonary arterial hypertension, cancer and airway constrictive diseases." (PMID 30696477, 2019). "Animal studies suggest a significant correlation between the expression of the pulmonary arterial hypertension-related gene BMPR2 and the hypoxia-sensing gene HIF1A during short-term high-altitude acclimatization." (PMID 41404581, 2025). "Pulmonary arterial hypertension (PAH) is a progressive and complex pulmonary vascular disease, with HIF1A identified as a potential biomarker and therapeutic target for PAH." (PMID 39272451, 2024). "Resveratrol inhibits pulmonary artery smooth muscle cell proliferation and right ventricular remodeling in pulmonary hypertension by regulating Nrf2, SIRT1 pathway and HIF-1α expression." (PMID 37779908, 2023). "The stabilizing HIF-1α can also induce numerous physiological responses to compensate for the decreased tissue oxygen supply, including the production of erythropoietin (EPO), which can cause an increase in hemoglobin, may result in secondary erythrocytosis and pulmonary hypertension." (PMID 37887394, 2023). "ZFC3H1 promotes the expression of BRD4 and HIF1a in PASMC, and its inhibition leads to the down-regulation of BRD4 and HIF1a and the reversal of the PAH phenotype in a murine model of pulmonary hypertension." (PMID 38132114, 2023). "Chronic continuous hypoxia induced-HIF-1α and HIF-2α results in pulmonary hypertension, whereas chronic intermittent hypoxia induces HIF-1α but inhibits HIF-2α, generating systemic hypertension." (PMID 36147561, 2022).
pulmonary hypertension (continued). "On the other hand, exogenously added ADMA increased the stabilization of HIF-1α protein in HPAECs, further decreasing DDAH-1 expression and activating HIF-1α dependent pathways, resulting in the development of pulmonary hypertension phenotype." (PMID 34356605, 2021). "Other groups have shown that HIF-1α is upregulated in chronic hypoxia- and MCT-induced pulmonary hypertension." (PMID 30909527, 2019). "In an inducible HIF-1α endothelial-specific knock out mouse model, it was discovered that HIF-1α was necessary for formation of pulmonary hypertension in a chronic hypoxia model and fibrosis in a bleomycin model." (PMID 31380363, 2019). "This aligns with studies on the influence of arsenic sulphide on the spread of cancer to other parts of the body through the HIF-1α/VEGF pathway, emphasizing comparable connections between substances produced during metabolism and changes in the genes in pulmonary hypertension." (PMID 39635438, 2024). "In pulmonary arterial hypertension, hypoxia-induced mROS inhibit HIF-1α hydroxylation via the HIF-1α/PDK1/PDK2/p-PDH-E1α axis, triggering glycolytic shift in pulmonary artery smooth muscle cells (PASMCs), leading to lactate accumulation and histone lactylation." (PMID 39010066, 2024). "By establishing a rabbit model of pulmonary hypertension, it was found that TPT could improve hypoxia-induced pulmonary vascular remodeling in PAH by inhibiting the expression of HIF-1α." (PMID 36139386, 2022). "HIF-1α L1Cre mice displayed a similar pattern of increased systemic blood pressure, metabolic rate and impaired vascular relaxation without features of pulmonary hypertension, polycythaemia or renal dysfunction under normal conditions." (PMID 34114090, 2021). "Furthermore, HIF-1α expression was partially responsible for CTGF expression, an indicator of endoMT in PMVEC in pulmonary fibrosis induced pulmonary hypertension." (PMID 31380363, 2019). "Interestingly, specific deletion of HIF-1α in the endothelium of a single organ, the lung, displays a similar pattern of increased systemic blood pressure, without any evidence of pulmonary hypertension." (PMID 34114090, 2021). "Mouse models of Chuvash polycythemia confirmed the phenotype of increased ventilation and pulmonary hypertension found in humans and further demonstrated that the effects seen in the disease are primarily HIF-2α driven as opposed to HIF-1α driven." (PMID 24201705, 2014).
ischemic stroke (96 papers, 2011 to 2026). A stroke disorder caused by obstruction of blood flow to the brain, due to thrombotic (local blood clot formation) or embolic (due to a blood clot or other material traveling from another site) event. "The data on the role of Hif-1α in the pathogenesis of brain damage associated with the development of ischemic damage such as ischemic stroke, hemorrhage, and circulatory arrest are contradictory." (PMID 39684384, 2024). "This study reveals the specific mechanisms underlying the effects of HIF‐1α on ischemic stroke (IS)." (PMID 39295108, 2024). "During the acute phase of ischemic stroke, the levels of HIF-1α and VEGF proteins in SIRT3-deficient mice increased, resulting in more severe BBB damage." (PMID 37627275, 2023). "A similar work has been reported in which neuronal Hif1α and Hif2α deficiency improves neuronal survival and sensorimotor function in the early acute phase after ischemic stroke." (PMID 34675764, 2021). "Here, we investigated the serum concentrations of miR‐210 and HIF‐1α, as possible diagnostic and/or prognostic markers for ischemic stroke (IS)." (PMID 34708885, 2021). "There is shortage of reliable biomarkers for ischemic stroke (IS), and we therefore investigated the serum concentrations of microRNA‐210 (miR‐210) and hypoxia inducible factor‐1α (HIF‐1α), as possible diagnostic and/or prognostic markers for IS." (PMID 34708885, 2021). "Further investigation is required to elucidate the specific regulatory role of HIF-1α and ferroptosis in ischemic stroke." (PMID 40552324, 2025). "All four biomarkers (SRC, TLR8, FCAR, and HIF1A) were significantly upregulated in ischemic stroke patients compared to healthy controls." (PMID 40948644, 2025). "Twelve genes have been reported as potential regulators of HT in ischemic stroke in previous studies: Casp3, Csf2, Ctnnb1, Cxcl12, Hif1a, Il1b, Mtor, Ptgs2, Ptprc, Tlr2, Tlr4, and Vcam1." (PMID 40002863, 2025). "We discuss how central metabolic sensors like AMPK, mTOR, and HIF-1α oversee these metabolic shifts in response to disease-targeted pathologies in Alzheimer’s, Parkinson’s, Multiple Sclerosis, ischemic stroke, and traumatic brain injury." (PMID 41288829, 2025). "The evidence indicates that the therapeutic effect is exerted via the HIF-1α/EPO/VEGFA signaling pathway with regard to ischemic stroke." (PMID 40166460, 2025). "Genetic neuronal HIF-1α and HIF-2α deficiencies triggered neuronal survival and sensorimotor function in an ischemic stroke model." (PMID 38674050, 2024). "HIF‐1α silencing attenuates inflammation and oxidative stress in ischemic stroke male rats and oxygen‐glucose deprivation/reoxygenation (OGD/R) mice hippocampal cells via the CXCR4/NF‐κB pathway." (PMID 39295108, 2024). "We detected that hypoxia-inducible factor-1α (HIF-1α), an indicator of ischemic stroke, was highly upregulated at both the protein and mRNA levels under OGD conditions." (PMID 38791263, 2024). "Activation of Nrf2 and HIF-1α exerts neuroprotective effects in models of neurodegenerative diseases such as Parkinson’s disease, Alzheimer’s disease, and ischemic stroke." (PMID 39063958, 2024). "Enhanced HIF-1α levels after ischemic stroke appear to be involved in RIPK3/MLKL activation, leading to activation of the NLRP3 inflammasome." (PMID 38674050, 2024). "Decreased LC3-II and HIF-1α expressions and increased p62 autophagy-related protein expression were observed following curcumin administration after an ischemic stroke." (PMID 37915409, 2023). "Vascular endothelial growth factor (VEGF) is one of the downstream target genes of HIF-1α, which is extensively involved in the pathological process of ischemic stroke." (PMID 36819784, 2023).
ischemic stroke (continued). "A previous study showed that the Bu Yang Huan Wu decoction can mitigate reperfusion injury after ischemic stroke in rats by inhibiting HIF-1α and VEGF while promoting β-ENaC expression." (PMID 38132462, 2023). "Exercise preconditioning enhanced HIF-1α expression, contributing to elevated glucose metabolism and ATP production rates after ischemic stroke." (PMID 35350755, 2022). "Our results showed that NADPH oxidase inhibition with inhibitor apocynin significantly reduced HIF-1α increase induced by 2 hours of MCAO, providing another strategy to regulate HIF-1α expression after ischemic stroke." (PMID 34434231, 2021). "NAC protects neurons against ischemia via HIF1 α overexpression in a rodent model of ischemic stroke." (PMID 34445365, 2021). "Future studies are needed to focus on certain types of cells and bidirectional functions to gain a better understanding of HIF-1α in pre-clinical models of ischemic stroke before progressing to clinical trials." (PMID 34966392, 2021). "In the present review, we elaborate on the regulatory mechanisms of HIF-1α and its various roles in ischemic stroke, specifically in four main types of cells in the NVU (i.e., neurons, astrocytes, endothelial cells, and microglial cells)." (PMID 34966392, 2021). "Because HIF-1α has various physiological functions in different types of cells, its phenotype becomes more complex under the context of ischemic stroke." (PMID 34966392, 2021). "In contrast, at D1 after ischemic stroke, Hif-1a, VEGF-A, Ang-2, TGF-β, and PDGF-β mRNA were significantly increased in NDI group compared with NS group." (PMID 34305641, 2021). "miR-140-3p was evidenced to transcriptionally regulate the hypoxia-inducible factor-1α (HIF-1α), and play antioxidative and cytoprotective roles under ischemic strokes." (PMID 35083214, 2021). "Recent representative translational studies that propose novel therapeutic options targeting HIF-1α for ischemic stroke are also discussed." (PMID 34966392, 2021). "In summary, we have provided strong evidence on the effectiveness of HIF-1α activation in alleviating brain damage after ischemic stroke." (PMID 34205911, 2021). "A growing number of pre-clinical studies in rodents suggests that the activation of HIF-1α signaling pathway prior or shortly after ischemic stroke reduces tissue damage and increases functional recovery from ischemic stroke." (PMID 34912224, 2021). "The pathophysiological function of HIF-1α in neurons varies, with contradictory effects on ischemic stroke." (PMID 34966392, 2021). "The relatively reduced induction of HIF-1α in haplogroup F1 cybrids after hypoxia-ischemia further supports the clinical findings of a vulnerability to ischemic stroke in patients harboring mtDNA haplogroup F1." (PMID 32796743, 2020). "The data suggest ischemic stroke resulted in renal hypoxia and is evidenced by elevated expression of HIF1α." (PMID 31784544, 2019). "Our results establish that ischemic stroke-mediated stabilization of HIF1α induces the expression of ZEB2." (PMID 31784544, 2019). "We found that ischemic stroke and the resultant hypoxic injury manifested in the elevated expression of HIF1α in various organs including kidney." (PMID 31784544, 2019). "In the early phase of ischemic stroke, exposure of mice brain to the hypoxic stimulus results in an induction of HIF-1α protein expression throughout the brain." (PMID 30622459, 2018). "Neuroprotection via HIF-1α stabilization following ischemic stroke is still a controversial topic due to its link to a vast variety of genes that mediate both adaptive and pathological processes." (PMID 30671433, 2018). "The intervention of the HIF-1α related pathway can be a potential target for the treatment of hypoxic injury in central nervous system disorders, such as ischemic stroke and hypoxic encephalopathy." (PMID 28590414, 2017).
ischemic stroke (continued). "Although the experimental evidence from in vitro and in vivo studies showed that the level of HIF-1α is significantly upregulated in the focal ischemic brain, the role of HIF-1α in the pathophysiology of ischemic stroke is controversial." (PMID 28697748, 2017). "It is essential to further our understanding of these downstream effects of HIF-1α as this will assist in the development of neuroprotective treatments for hypoxic brain disorders, such as ischemic stroke or hypoxic encephalopathy." (PMID 28590414, 2017). "It is well known that HIF-1α plays a vital role in attenuating brain tissue damage through promoting adaptive response during ischemic stroke." (PMID 28979191, 2017). "To explore the possible mechanism of EPC transplantation-mediated BBB protection after ischemic stroke in diabetic mice, we examined the level of HIF-1α in the ischemic brain of diabetic mice after EPC treatment." (PMID 28697748, 2017). "Hitherto, only a few studies have investigated the role of HIF-1α in neuronal tissues or animal models of ischemic stroke and demonstrated potential benefits of such therapy." (PMID 28590414, 2017). "Our results therefore suggest that HIF-1α in microglia is a novel therapeutic target to protect neuronal survival following an acute phase of ischemic stroke." (PMID 29340071, 2017). "Subsequently, we found that administration of miR-335 mimic immediately after eMCAo inhibited Hif-1α expression and consequently reduced the infarct volume by 60% in ischemic stroke models." (PMID 26030758, 2015). "Inhibition of Hif-1α in the early phase of ischemic stroke by using siRNAs has been found to bring about reduction of infarct damage." (PMID 26030758, 2015). "The Hif-1α gene expression increased from the onset of ischemic stroke and peaked at 6 hrs post occlusion and progressively decreased until 24 hrs." (PMID 26030758, 2015). "Related studies have reported the detrimental effects of HIF‐1α in ischemic brain injury, including severe inflammatory responses and enhanced apoptosis following ischemic stroke, suggesting that HIF‐1α may act as a mediator of neuroinflammation." (PMID 40019048, 2025). "These divergent findings might be attributed to disparate regulatory mechanisms governing the response to ischemic stroke mediated by HIF-1α." (PMID 40552324, 2025). "Also, SIRT3 protects the integrity of the blood-brain barrier (BBB) in ischemic stroke mice by regulating the HIF-1α/VEGF pathway in astrocytes, reducing inflammatory responses and neuronal apoptosis." (PMID 40969935, 2025). "Therefore, it is necessary to further investigate the complex and significant role that HIF-1α plays in ischemic stroke." (PMID 36819784, 2023). "It was reported that HIF1α could regulate the progress of neurological symptoms after ischemic stroke." (PMID 37533068, 2023). "SIRT3 helps in relieving brain edema and BBB damage after ischemic stroke, which might be achieved by increasing TJ proteins ZO-1 and Occludin by regulating the HIF-1α signaling pathway." (PMID 37627275, 2023). "Actually, the HIF-1α/NLRP3 pathway has been recognized as a potential molecular target for treating ischemic stroke and traumatic brain injury because it regulates microglia activation and inflammatory cytokines release in the inflammatory cascade after brain injury." (PMID 36944982, 2023). "Based on the previous searches and reports, it was hypothesized that the significant protective effects of GP17 against ischemic stroke might be exerted via autophagy via Hif-1α/BNIP3 pathway or NAMPT-mediated pathway, namely SIRT1/2/3." (PMID 36572901, 2022). "This outcome is a reminder that regulating HIF-1α expression in a time-dependent manner may potentially focus on the further treatment of ischemic stroke." (PMID 35350755, 2022). "Furthermore, HIF‐1α has been reported to play a key role in regulating the final outcome of hypoxic diseases such as ischaemic stroke." (PMID 36054154, 2022).